EGFR (epidermal growth factor receptor)
Diseases named in the same sentence as EGFR in open-access papers (continued):
Sharing a sentence is not in itself a finding about the gene and the disease.
Skin rash (continued). "Thus, following on from several case/small studies, there have been five randomized trials of the use of standard tetracycline and tetracycline-class (minocycline and doxycycline) antibiotics in the treatment of skin rash in patients receiving EGFR-targeted therapies." (PMID 23801914, 2013). "However, many studies confirmed that patients with a skin rash may have a better response to EGFR-TKIs and an even better prognosis." (PMID 23383079, 2013). "Thus, a skin rash may be more efficient in predicting the EGFR-TKI response rate of patients with NSCLC than clinic pathological characteristics." (PMID 23383079, 2013). "This study provides empirical evidence that skin rashes that occur after EGFR-TKI (i.e., gefitinib and erlotinib) treatment may be an efficient clinical marker for the prediction of the response of patients with NSCLC to EGFR-TKI treatment, including for the ORR and DCR." (PMID 23383079, 2013). "Indeed, in this study, 3 cases without EGFR mutation treated by gefitinib resulted in PD and skin rash did not occurred at all." (PMID 23420789, 2013). "As a consequence the authors concluded that because of the preliminary benefits observed and the general acceptance of tetracycline for the treatment of skin rashes, there should be no objection to its prescription to reduce the severity of the rash associated with EGFR-targeted agents." (PMID 23801914, 2013). "Furthermore, from a clinical point of view, the only parameter which has been constantly associated with a high probability of response, prolonged progression-free survival (PFS) and median Overall Survival (mOS) to anti-EGFR moAbs treatment is the development of skin rash." (PMID 21283802, 2011). "Furthermore, the severity of skin rash during the treatment with anti-EGFR mo-Abs has been constantly reported as a predictive factor for response and survival, and this was also the case in the present study, since the severity of skin rash was an independent predictive factor for TTP and OS." (PMID 21283802, 2011). "Rash is the most common toxicity reported in patients treated with the anti-EGFR monoclonal antibodies cetuximab and panitumumab, and in patients treated with the EGFR tyrosine kinase inhibitors gefitinib and erlotinib, and its occurrence with these agents is occasionally severe." (PMID 16622465, 2006). "Recent reports have suggested that skin rash may predict clinical response to EGFR inhibitors." (PMID 14661047, 2003). "Skin rash is a main side effect of EGFR-TKI therapy, and approximately two-thirds of NSCLC patients treated with EGFR-TKI experience dermatological toxicity, including skin rash." (PMID 33592873, 2021). "Even with targeted therapies, skin rash and hypertension was found to be positively correlated with improved PFS and OS for EGFR antibodies and VEGF inhibitors, respectively." (PMID 32802390, 2020). "Therefore, if we assume that the anti-tumor effect of erlotinib is mostly mediated by EGFR inhibition, it is theoretically possible to reduce the risk of skin rash with a negligible loss in therapeutic effect by optimizing the dose to inhibit EGFR but not STK-10." (PMID 30868372, 2019). "Local prevention of EGFR inhibition in the skin might prevent or cure the skin rash caused by disruption of normal EGFR functions by the targeting therapeutics, without affecting anticancer activity, ensuring continuous treatment and, ultimately, clinical benefits." (PMID 31703435, 2019). "Afatinib has also been combined with cetuximab (Merck), a chimeric monoclonal anti-EGFR antibody and has demonstrated promising clinical activity in EGFR-mutant NSCLC, albeit at the cost of high rates of diarrhea and skin rash." (PMID 28443282, 2017). "Inhibition of EGFR signaling in these healthy tissues by either anti-EGFR antibodies or TKI result in adverse effects, most commonly skin rash or gastrointestinal disorders." (PMID 27153091, 2016).
Skin rash (continued). "In the present study, rash occurred in ten patients (25.0 %) in the N-IRI group, which represents a lower frequency than that reported for patients receiving other anti-EGFR monoclonal antibodies, such as cetuximab or panitumumab." (PMID 25185971, 2015). "Moreover, similar results were obtained in the EGFR mutation-negative patients, suggesting that erlotinib may be effective in EGFR mutation-negative patients, in whom EGFR-TKIs are considered to be less effective, on developing a rash." (PMID 23420613, 2013). "Furthermore, skin rash may be efficient prognostic factors for patients with NSCLC using EGFR-TKIs." (PMID 23383079, 2013). "Although skin rash may be a pharmacodynamic marker of drug action, its predictive value and potential as a surrogate marker for response to EGFR-targeted agents depends on the correlation of HER-kinase signaling in paired skin and tumour tissue which requires further investigation." (PMID 16306877, 2006). "Skin rash of grade 2 and greater (NCI-CTC) is dose dependent and occurs in 20–50% of patients treated with EGFR-directed therapies such as gefitinib, erlotinib and cetuximab." (PMID 16306877, 2006). "As it is difficult to distinguish rosacea-like dermatitis from acne vulgaris, which is not related to EGFR inhibitors, the management of EGFR inhibitor-induced skin rash plays an important role during cancer treatment." (PMID 40888993, 2025). "The pathogenesis of EGFR inhibitor-induced skin rash has not been clearly identified; however, an inflammatory response mediated by chemical mediators has been suggested." (PMID 40888993, 2025). "A phase II study showed that osimertinib (160 mg/day) achieved an objective response rate (ORR) of 27.5% and a DCR of 82.5% in EGFR T790M-positive NSCLC with BM/LM, the mPFS was 5.7 months, and the common AEs included decreased appetite, diarrhea, and skin rash, most grade 1 or 2 levels." (PMID 39949743, 2025). "Skin rashes generally correspond to the EGFR-targeted therapy efficacy, which does not apply to this case due to the opposing effects of these two agents in the skin used in this study." (PMID 38202120, 2023). "Since the multiple functions of dWAT are closely related to EGFRI-induced skin toxicities and a reduction in dermal fat has been observed in EGFR-depleted mice, we investigated whether dWAT plays a central role in EGFRI-induced rash." (PMID 35324426, 2022). "For non-hematological adverse effects during EGFR-TKIs therapy, the most common events were skin rash, diarrhea, fatigue, nausea, vomiting, increased ALT levels, and pneumonitis." (PMID 35145913, 2022). "These blood biomarkers can predict drug efficacy or serious skin toxicity earlier than the occurrence of a skin rash, and it is more appropriate to predict the effect of EGFR inhibitors for patients who are not prone to skin toxicity." (PMID 35223483, 2022). "Skin rash was the most common (64.00% in the combination group and 70.15% in the EGFR-TKI monotherapy group) (p = 0.804), followed by elevated liver enzymes (62.00% in the combination group and 50.74% in the EGFR-TKI monotherapy group, p = 0.228)." (PMID 34034713, 2021). "Moreover, augmented EGFR levels in the BioMAP HDF3CGF systems seem to be common to all EGFR kinase inhibitors and correlate with skin rash." (PMID 33777941, 2021). "The pathogenesis of EGFR inhibitor-induced rash is not well clarified: however, certain inflammatory cytokines released by EGFR expressed keratinocytes can be involved with the rash formation." (PMID 29719624, 2018). "By contrast, in specific reviews of EGFR inhibitor-induced skin reactions, the use of retinoids for skin rash has not been generally recommended due to the lack of comedones and the possible aggravation of xerosis and eczema." (PMID 24396465, 2014). "Overall, the skin rash after using EGFR-TKI (i.e., gefitinib and erlotinib) may be an efficient clinical marker for predicting the response of patients with NSCLC to EGFR-TKIs including the ORR and DCR." (PMID 23383079, 2013).
Skin rash (continued). "The median overall and progression-free survival was similar between the two groups, indicating that the preemptive treatment of skin rash had no adverse impact on the outcome from anti-EGFR therapy." (PMID 22997576, 2012). "In a phase I study of RG83852, no skin rash was observed at doses that produced a high level of saturation of EGFR in vivo." (PMID 22761877, 2012). "A papulopustular (also called acneiform) skin rash is a common toxicity observed with both EGFR-targeting mAb and tyrosine kinase inhibitors (TKI), with a reported incidence of up to 80% in patients treated with EGFR-targeting agents." (PMID 22761877, 2012). "The pathophysiologic basis of skin rash in patients treated with EGFR signalling inhibitors is not clear." (PMID 16622465, 2006). "Our study provides a molecular rationale for the skin rash commonly observed with EGFR-targeted therapies (such as gefitinib and cetuximab) but not with therapies that target the HER2 receptor (such as pertuzumab and Herceptin)." (PMID 16306877, 2006). "However, skin rash as an adverse event of EGFR-TKIs did not significantly influence the treatment efficacy of first-line EGFR-TKIs (PFS HR 0.86 [95% CI 0.54–1.35], p = 0.51; OS HR 0.73 [95% CI 0.40–1.33], p = 0.30)." (PMID 37221285, 2023). "To date, no prophylactic methods for EGFR inhibitor-induced skin rashes have been established." (PMID 38092882, 2023). "The evidence indicates that a higher incidence of skin rashes in males might be attributed to the effects of a lack of skincare, male hormones, and the secretion of anti-EGFR antibodies in sweat." (PMID 36980549, 2023). "Thus, focused patient education on the importance of skincare, particularly in the summer, may reduce rash severity in patients, especially males, with CRC or HNC being treated with anti-EGFR antibodies." (PMID 34441007, 2021). "However, the relationship between EGFR inhibitor-induced rash and season or sex has not been investigated." (PMID 34441007, 2021). "The higher incidence of skin rashes in males during summer may be attributed to the effects of ultraviolet (UV) light, lack of skincare, male hormones, and secretion of anti-EGFR antibodies into the sweat." (PMID 34441007, 2021). "Regarding toxicity, first-generation EGFR-TKIs showed diarrhea in 57%, skin rash in 48%, AST elevation in 25%, and interstitial lung disease in 2% of patients, while osimertinib showed milder toxicities (diarrhea 58%, skin rash 25%, AST elevation 9%, and interstitial lung disease 4%)." (PMID 31049758, 2019). "Topical restoration of EGFR signaling in the skin might mitigate skin rash in patients treated with EGFR-targeting therapies, without affecting anticancer activity in tumor lesions." (PMID 31703435, 2019). "This compensation of EGFR inhibition by HGF/MET signaling might also happen in skin cells and could explain why higher plasma concentrations of HGF correlate with less severe EGFRI-induced skin rash." (PMID 28456787, 2017). "However, a possible activation/inhibition of EGFR in skin cells by calcitriol does not seem to be strong enough to measure an according increase/decrease in severity of EGFRI-induced rash." (PMID 28456787, 2017). "However, only about 1% of the patients in phase I and II studies with pertuzumab developed skin rash greater than grade 1 which did not demonstrate the rash characteristics typical for EGFR inhibitor therapy; (S Kelsey, Genentech, personal communication)." (PMID 16306877, 2006). "Interestingly, a recent study described skin rash in 61% of 15 patients with metastatic breast cancer treated with erlotinib even though 14 of the 15 tumours were EGFR negative and had no objective clinical responses." (PMID 16306877, 2006).
Skin rash (continued). "Furthermore, we did not investigate the relationship between the severity of skin rash and the treatment efficacy of EGFR-TKIs because we did not obtain detailed information on the grade of skin rash, namely, the extent to which skin rash covered the body surface area of patients." (PMID 37221285, 2023). "However, EGFR T790M shares a similar ATP affinity with wild-type (WT)-EGFR, which limits the ability to achieve plasma concentrations sufficient to inhibit EGFRT790M and results in skin rash and diarrhea in patients, thereby failing to overcome T790M-mediated resistance." (PMID 36209184, 2022). "However, our study revealed that patients with NSCLC that had a rash had a higher EGFR-TKI response rate compared with patients without a rash regardless of whether they were White or Asian." (PMID 23383079, 2013). "In addition, our results demonstrated no nimotuzumab related skin rash was reported in our 42 patients, which could be explained by the property that nimotuzumab has lesser affinity and hence binds with less avidity than other monoclonal EGFR antibodies (cetuximab and panitumumad)." (PMID 27016412, 2016).
oral squamous cell carcinoma (133 papers, 1989 to 2026). "Here the authors report the results of a phase II trial to evaluate the diagnostic accuracy of an EGFR-targeted FMI for intraoperative margin assessment in patients with oral squamous cell carcinoma." (PMID 37587149, 2023). "Recent studies have suggested that acquired resistance to anti-epidermal growth factor receptor (EGFR) therapies such as cetuximab are in part caused by genetic alterations in patients with oral squamous cell carcinoma (OSCC)." (PMID 31434965, 2019). "This study was designed to explore the relationship between epidermal growth factor receptor (EGFR) CA repeats polymorphism and protein expression in oral cavity squamous cell carcinoma (OSCC)." (PMID 28694429, 2017). "Elevated EGFR expression in oral squamous cell carcinomas have also been associated with larger tumor and advanced stage and hence, a poor prognosis." (PMID 26675419, 2015). "Oral squamous cell carcinoma (OSCC) is an aggressive malignancy frequently characterized by dysregulated epidermal growth factor receptor (EGFR) signaling." (PMID 40472740, 2025). "In contrast, ADAMTS1 overexpression promoted lymph node metastasis through the upregulation of EGFR, pEGFR, and pAKT in oral squamous cell carcinoma." (PMID 40867252, 2025). "The results of immunohistochemical analysis unveiled that, among the 52 oral squamous cell carcinoma cases examined, 42.3% (22/52) and 44.2% (23/52) showed high expressions of p-EGFR and Mcl-1, respectively." (PMID 38888847, 2025). "EGFR tyrosine kinase inhibitor (TKI) resistance in oral squamous cell carcinoma (OSCC) can arise from various mechanisms." (PMID 39863836, 2025). "Curcumin, for instance, has been shown to inhibit proliferation and induce apoptosis in oral squamous cell carcinoma (OSCC) via EGFR pathway suppression and modulation of NF‐κB, AP‐1, and other signaling cascades." (PMID 40933552, 2025). "Ligand-induced activation of EGFR promotes, while EGFR signaling blockage inhibits, the autocrine uptake of oral squamous cell carcinoma cell-derived EVs through regulating macropinocytosis." (PMID 38259097, 2024). "Positive expression of EGFR has already been reported for oral squamous cell carcinoma, representing the most common type of malignancy in the oral cavity and esophagus." (PMID 38542206, 2024). "In conclusion, we have shown that EGFR-targeted fluorescence molecular imaging with cetuximab-800CW accurately identifies tumor-positive surgical margins of oral squamous cell carcinoma." (PMID 37587149, 2023). "This combination aids in tracking metastatic lymph nodes in cases of oral squamous cell carcinoma (OSCC) where there is an overexpression of the epidermal growth factor receptor (EGFR)." (PMID 37736720, 2023). "Epidermal growth factor receptor (EGFR) is frequently overexpressed in oral squamous cell carcinoma (OSCC), and EGFR‐targeting therapeutics have been widely employed to treat patients with a variety of carcinomas including OSCC." (PMID 37341071, 2023). "Around 80% of oral squamous cell carcinomas exhibit EGFR overexpression, which promotes the proliferation and differentiation of keratinocytes." (PMID 37370896, 2023). "Inhibiting EGFR can effectively inhibit the progression and lymph node metastasis of oral squamous cell carcinoma (OSCC) because OSCC is a type of cancer with high EGFR expression." (PMID 36899380, 2023). "Oral squamous cell carcinoma (OSCC) frequently carries high epidermal growth factor receptor (EGFR) expression." (PMID 36611972, 2023). "Similar studies in Oral Submucous Fibrosis showed increased immunohistochemical expression of EGFR and Oral Squamous Cell Carcinoma." (PMID 36010285, 2022). "Among various biomarkers, EGFR overexpression has an unfavorable clinical outcome, poor prognosis, and low survival rates in Oral Squamous Cell Carcinoma (OSCC)." (PMID 36010285, 2022). "It has been reported that IFIT1 and IFIT3 are critical for EGFR recycling and activation in oral squamous cell carcinoma." (PMID 35280763, 2022).